PARP1 (poly(ADP-ribose) polymerase 1)
Diseases named in the same sentence as PARP1 in open-access papers (continued):
Sharing a sentence is not in itself a finding about the gene and the disease.
tumor (continued). "Up-regulation of PARP-1 expression and activity has been observed in a variety of human tumours." (PMID 24191908, 2013). "In contrast, others have reported that inhibition or the absence of PARP-1 is associated with reduced risk of malignancy by inducing tumor cell apoptosis." (PMID 20196871, 2010). "However, after full-dose chemotherapy, fewer than 5% of tumor cells contained activated caspase-3, whereas cleaved PARP-1 was detected in up to 40% of tumor cells." (PMID 19247492, 2009). "A higher level of PARP-1 mRNA was observed in malignant lymphoma cells compared with normal lymph nodes and in colorectal adenocarcinoma biopsies compared with adjacent non-tumour tissues and hyperplastic polyps." (PMID 19568233, 2009). "Synthetic lethal interactions between the FA pathway and other DNA damage response genes such as ATM, PARP1 and NBS1 have been identified recently, stimulating interest in determining if FA pathway inhibitors would selectively target tumor cells deficient in these genes." (PMID 20043851, 2009). "Subsequently, those patients might benefit from treatments with agents selectively targeting BRCA mutant tumour cells, such as poly(ADP-ribose) polymerase 1 inhibitors." (PMID 18628764, 2008). "In addition, therate of population aging was higher and MRDT was lower in the PARP-1−/− tumor-bearing mice as compared to the PARP-1+/+ group." (PMID 19415146, 2008). "Hence, PARP1 hyperactivation reflects a prodeath signal in tumor growth." (PMID 40904702, 2025). "Interestingly, PARP1 is itself a MIG, raising the possibility that minor splicing inhibitors could also interact indirectly with BRAC1/2 mutations to reduce tumour burden." (PMID 40624356, 2025). "Furthermore, high PARP2 expression, but not PARP1, showed an association with right-sided tumors, late pathological tumor stages, and disease-free survival." (PMID 40573300, 2025). "Notably, the PARP1 inhibitor Olaparib significantly reduces tumor burden in Nudt13VillKO mice, implying that CRC patients with low NUDT13 protein levels may benefit from Olaparib treatment." (PMID 39921866, 2025). "Furthermore, differences in uptake were found within the tumour itself, suggesting that [18F]PARP1‐inhibitor PET may be able to visualise differences in PARP1 expression within a tumour and between different metastases in the same patient." (PMID 40923371, 2025). "We propose this increased caspase expression is used to support tumor stress adaptation, through enhanced PARP1 activity, autophagy, and DDR signaling, and may be a targetable vulnerability, particularly in the context of BRCA1 or other potential synthetic lethal mutations identified here." (PMID 39982959, 2025). "Therefore, as one of the important targets of AR synthesis and a participant in AR signal transduction, PARP1 has potential in tumor treatment and may provide an effective treatment strategy for mCRPC and mRCC patients." (PMID 38965120, 2024). "However, PARP-1 also plays a role in promoting tumor progression in several tumor models." (PMID 38965120, 2024). "Hence, inducing apoptosis in tumor cells can be achieved by suppressing PARP-1 activity." (PMID 39620145, 2024). "Additionally, we found support for the SL interaction between LIG1 and PARP1 and EME1 and PARP1 by analyzing the coexpression of LIG1, EME1, or FAAP24 and PARP1 in relation to the tumor, node, metastasis (TNM) stage of PCa samples (P value for LIG1-PARP1 < 0.001; P value for EME1-PARP1 < 0.05)." (PMID 39718835, 2024). "Moreover, DTYMK and PARP1 were also variably expressed in UM tumor cells between patients." (PMID 39195238, 2024). "Moreover, PARP1 inhibitors have been shown to play an anti-tumor role in many tumors." (PMID 38907095, 2024). "Moreover, the use of DSF/Cu2+ in conjunction with an anti-PD-1 antibody which jointly inhibits both PARP1 and the PD-1/PD-L1 pathway, not only resulted in reduced tumor cell viability but also led to an increase in the number of T cells that infiltrate the tumor." (PMID 37326784, 2023).
tumor (continued). "As a consequence, PARPi might also radiosensitize tumor cells with non-HR deficiencies by suppressing PARP-1-dependent c-NHEJ." (PMID 37629155, 2023). "Indeed, once the tumour is formed, PARP-1 expression tends to be increased." (PMID 37686260, 2023). "Additionally, simultaneous inhibition of Hsp90 and PARP-1 via hyperthermia could sensitize tumors to HR inactivation, impairing tumor cell repair mechanisms." (PMID 36900195, 2023). "However, transgenic mice deficient in PARP-1 expression do not show any spontaneous tumour development, even though they are more sensitive to alkylating agents which provoke in these mice liver and colorectal cancers with a greater frequency." (PMID 37686260, 2023). "In addition, cleavage of caspase-9/-3 and PARP1 was increased in PI3/SLPI-deficient cells upon TRAIL treatment, substantiating the tumor-protective role of these two peptidase inhibitors through regulation of both intrinsic and extrinsic apoptosis pathways downstream of TSPO." (PMID 37158962, 2023). "Additionally, in those tumours, PARP-1 and CSC markers were positively correlated." (PMID 36902215, 2023). "In addition, Nile red staining showed that SKA3 overexpression increased triglyceride levels in tumours, which could be reversed by PARP1 and HIF-1a knockdown." (PMID 37821935, 2023). "However, once a tumour occurs, PARP-1 facilitates its progression." (PMID 36902215, 2023). "Increased expression of PARP-1 and PARylation may stimulate tumor growth." (PMID 36077221, 2022). "BRCA1-deficient tumour cells are sensitive to poly(ADP-ribose) polymerase (PARP1) inhibitors (PARPi) through a mechanism of synthetic lethality, an interaction in which inhibition of PARP1 results in loss of cell viability specifically in cells deficient in HR." (PMID 35619904, 2022). "Inhibition of PARP1/2 leads to the accumulation of single strand breaks, causing double strand breaks that require repair by homologous recombination (HR), and tumor cells lacking BRCA1 or BRCA2, which play key roles in the HR pathway, are uniquely sensitive to PARP inhibition." (PMID 35396812, 2022). "Thus, direct modification of EZH2 by PARP1 may be involved in regulating the response of tumor cells to DNA damage and oxidative stress, but it remains unclear which downstream signaling pathways may be altered as a result of such modifications." (PMID 36263120, 2022). "Furthermore, challenges in efficient delivery of such compounds across the BBB are a major clinical consideration; however, at least for PARP1 inhibitors, early indications are encouraging in that therapeutically active doses can be achieved at the tumour site." (PMID 34036721, 2022). "Interestingly, PARP1 overexpression led to opposite effects in tumor cells and stroma cells." (PMID 35875162, 2022). "Given this functional interplay, it has been postulated that FA dysfunctional tumours, or targeting of the FA pathway, may render them sensitive to PARP1 inhibitors, as well as a multitude of other drug targeting strategies within the FA and related DDR pathways." (PMID 34036721, 2022). "Moreover, the different roles of PARP1 expression in tumor cells and stroma cells were revealed via multiplex immunofluorescence assay, and PARP1 expression in stroma cells may affect the response to PARP1 inhibitors." (PMID 35875162, 2022). "SSBs caused by chemical or physical interference, such as chemical reagents and ionizing radiation, may be repaired by PARP pathway, through the mechanism of PARP1/2 bind to DNA breaks and recruit repair enzymes via auto-PARylation, resulting in tumor cell survival." (PMID 36756144, 2022). "In addition, PARP1 was discovered to be a molecular target of anti-tumor drugs." (PMID 33747905, 2021).
tumor (continued). "Another possible reason for PARP1 overexpression is defective PARP1 cleavage, which leads to an imbalance of apoptosis induced by various chemotherapeutic drugs in tumor cells, suggesting that these patients with high PARP1 expression might be responsible for chemoresistance." (PMID 34531868, 2021). "Therefore, overactivation of PARP1 is an important part in the process of oxaliplatin-induced parthanatos, and it may also be a potential effective anti-tumor method." (PMID 33495407, 2021). "PARP1 may have both oncogenic and tumor suppressor functions in colorectal cancers." (PMID 33384409, 2021). "Because the clinical benefit of CDK4/6 or PARP-1 targeted inhibition as respective monotherapies might be, as also shown in other tumor entities, limited for BLCA, suitable combination therapies for these compounds are necessary for sufficient therapeutic efficiency." (PMID 33923231, 2021). "Additionally, they express PARP1 in almost 100% of tumour cells." (PMID 34440228, 2021). "Thus, studies have shown that the loss‐of‐function alterations of PARP1 led to a 100‐fold higher olaparib resistance than its wild‐type counterpart, and elevating the PARP1 expression may make tumours more sensitive to PARP inhibitors." (PMID 34761497, 2021). "Investigating whether PARP-1 expression in cases of early UM affects the prognosis is problematic, because, due to the small size of the tumor and its frequent location in the posterior part of the eyeball, obtaining tissues for histopathological examination is practically impossible." (PMID 33572586, 2021). "Hence, inhibition of this PARP1-mediated DNA repair may allow the damage to persist, resulting in strand breaks and ultimately tumour cell death." (PMID 34440228, 2021). "Another study showed that a loss of function in PARP-1 activated the epithelial–mesenchymal transition pathway through the increased expression of N-cadherin and ZEB-1 and the decreased expression of E-cadherin and β-catenin, which promote tumour progression through the TGF-β signalling pathway." (PMID 34830749, 2021). "From a therapeutic point of view, the germline variants found in genes involved in DNA damage response and double-strand repair mechanisms indicate the tumours could have been sensitive to the treatment with PARP1/2 inhibitors such as olaparib and niraparib through mechanisms of synthetic lethality." (PMID 34299215, 2021). "We acknowledge that other important aspects of crosstalk with the immune system might be evoked by this combination, such as modulation of the tumor microenvironment by both trabectedin and PARP1 inhibition and activation of the stimulator of interferon genes (STING) pathway." (PMID 34944915, 2021). "In addition, the western blot data of PC-3-transplanted tumor tissues demonstrated that the protein levels of Sp1, Sp3/4, Survivin, and Cyclin D1 were decreased, while the protein levels of c-Caspase 3 and c-PARP-1 were increased in the HD and PC groups (compared with the NC and LD groups)." (PMID 32851058, 2020). "In addition to reducing tumour penetrance, the absence of PARP1 was also associated with smaller tumour volume." (PMID 33050515, 2020). "Therefore, modulation of these PARP1 regulatory proteins may provide an alternate method of downregulating PARP1 activity or modulating the sensitivity of tumor cells to PARP inhibitors." (PMID 33015058, 2020). "Notably, tumor uptake at 2 h in a U87 subcutaneous model was reported as 0.17% ID/g (tumor: muscle = ~4.36) whereas in the U251 orthotopic model it was 0.43% ID/g (tumor: muscle = 13.7 ± 4.1) despite the same PARP1 expression levels in both U87 and U251 tissues." (PMID 32640708, 2020). "Additionally, caspase-3 activity increased in Parp1−/− cRb−/− RasV12 tumours, which may reflect the reduced tumorigenic potential of these cells." (PMID 33050515, 2020).
tumor (continued). "Thus, simultaneous inhibition of RAD52 and PARP1 might result in a robust dual synthetic lethality, effectively eradicating BRCA1/2-deficient tumor cells." (PMID 31615159, 2019). "In addition, MZF1‐AS1 binds poly(ADP‐ribose) polymerase 1 (PARP1) to facilitate its interaction with E2F transcription factor 1 (E2F1), resulting in transactivation of E2F1 and upregulation of MZF1 and other oncogenic genes associated with tumor progression." (PMID 31592410, 2019). "In addition, it has also been suggested that inhibitors of BRCA1 may sensitize tumor cells to the effect of targeted therapies such as PARP1 inhibitors." (PMID 29606576, 2018). "Consequently, tumor cells having low protein expression of MACROD2 may effectively enable PARP1-dependent DNA repair." (PMID 30034629, 2018). "Importantly, this also implies that healthy, HR-proficient cells are not targeted by PARP1-i, which makes this therapy particularly desirable for patients with HR-deficient tumours." (PMID 28427225, 2017). "Finally, to generalize the key role played by PARP1 basal expression in synergism, we asked whether enzyme basal expression might drive tumor cell response to other cytotoxics used in combination with PARP1 inhibitors." (PMID 28454547, 2017). "Consistently, blockade of CXCR2 systemically in mice instead of tumor cells only could reduce engraftment rates of tumor cells homing to liver after IR injury, indicating that CXCL1/CXCR2 signaling is critical in PARP-1-induced susceptibility of the liver to recurrence." (PMID 29179487, 2017). "Interestingly, LNT increased the cleaved Caspase 3 (C-Caspase 3) protein expression and decreased the cleaved PARP1 (C-PARP1) protein level, a hallmark of cell apoptosis occurrence, confirming that LNT really promoted tumor cell apoptosis via caspase 3-dependent pathway." (PMID 29156828, 2017). "Further, the fluorescent imaging agent PARPi-FL is able to accumulate in irradiated cell nuclei of tumor tissues, and its accumulation indicates, that it might be possible to use this or other PARP1 targeted imaging agents to delineate tissues exposed to radiation." (PMID 26808835, 2016). "Histological evaluation of tissue sections from tumor-bearing tongues confirmed that PARPi-FL could only be found in regions classified as tumor tissue in H&E stained sections, and that the tumors showed highly elevated PARP1 expression compared to normal mouse tongue." (PMID 26900125, 2016). "Within regions of viable tumor, scattered neoplastic cells exhibited morphological features of apoptosis, such as cell shrinkage, nuclear pyknosis and fragmentation, as indicated by immunohistochemical stains for cleaved PARP-1, a marker for chemotherapy-induced apoptosis." (PMID 27421768, 2016). "However, the density of PARP1-positive tumor cells varies in different areas." (PMID 26900125, 2016). "Microscopic evaluation revealed that PARPi-FL was able to, penetrate up to 300 μm deep into tumor tissue during the one minute application window, whilst being able to wash out from non-target areas during the cleaning steps, resulting in high contrast PARP1 staining of OSCC nuclei." (PMID 26900125, 2016). "The use of PARP-1 inhibitors in combination with standard chemotherapeutic agents also, seems attractive in the sense that sensitizing tumor cells to cytotoxic agents might enable the use of lower doses, while maintaining the same relative efficacy with reduced toxic side effects." (PMID 27220670, 2016). "However, further research is needed to investigate the role of PARP-1 in Walker 256 tumor cell." (PMID 26303118, 2015). "The direct action of PARP1 inhibitors on tumor cells may also be explained byanother mechanism." (PMID 26483957, 2015).
tumor (continued). "PARP-1 inhibition may have a clear benefit in tumour treatment by limiting the rate of cell proliferation and activation of NF-κB, leading to the suppression of both the inflammation and the expression of genes related to tumour progression." (PMID 26339143, 2015). "Since PARP1 inhibition has already been evaluated in numerous different adult-onset tumor types, a variety of potential biomarkers of DNA repair currently exist [i.e., γ-H2AX, poly(ADP-ribose)] and could be incorporated for evaluation in future pediatric trials." (PMID 23761859, 2013). "The decline in ascites production, tumor weight and vascular density was associated with a rapid decrease in Ki-67 expression (cell proliferation) and increases in TUNEL-positive lesions and expression of apoptotic proteins: caspase-3 (active) and PARP-1 (cleaved p85)." (PMID 21931707, 2011). "To investigate the in vivo regulatory role of MRPL21 in tumor progression, we established an HNSCC xenograft model by subcutaneously injecting cells harboring knockdown of MRPL21 and PARP1-overexpressing cells, as well as control cells, into nude mice." (PMID 40713706, 2025). "In endometrial cancer, the SNORD104/FBL complex enhances PARP1 mRNA translation to drive tumor progression, while FBL silencing disrupts this process, leading to tumor growth inhibition." (PMID 41463151, 2025). "qPCR analysis of the tumor tissue demonstrated that the expressions of DNA damage marker genes (TP53BP1, PARP1, and BRCA1), cGAS, STING, SEI1, and PD‐L1 were increased in melphalan or bortezomib treated mice." (PMID 40135791, 2025). "Particularly, the expression of DNA repair‐related genes PARP1 and TOP1 was identified exclusively in HBV‐positive tumours, which were validated through immunohistochemistry." (PMID 39799416, 2025). "The DNA repair pathway plays a role in tumor dissemination, and molecules such as poly (ADP-ribose) polymerase 1 (PARP1), NME/NM23 nucleoside diphosphate kinase 1 (NME1) and proliferating cell nuclear antigen (PCNA) are highly expressed in metastatic lesions." (PMID 39780291, 2025). "The research group also observed that PAR levels identified in tumor cells and xenografts overexpressing PARP1 more accurately predicted responses to PARP inhibitors than PARP1 expression alone." (PMID 41463185, 2025). "IHC analysis of tumor tissues further revealed significant downregulation of MRPL21, Ki67, and PARP1 in the drug-treated group." (PMID 40713706, 2025). "Among them, the expression of TIPRAP, WSCD1, TCP11L2, DPP4, CAB39 and PDPK1 were down-regulated, while PARP1, DEPDC1B, CKAP2, ORMDL2, MRPL44, POLD4 and TMEM187 were increased in tumor group." (PMID 39949782, 2025). "Sustained PARP1 activation leads to NAD+ depletion and mitochondrial dysfunction, contributing to inflammatory and tumour-promoting microenvironments." (PMID 41294806, 2025). "AARS1 catalyzes the lysine-alanylation (K-Ala) of poly (ADP-ribose) polymerase 1 (PARP1) in K621 peptides, suppressing PARP1 activity and cell apoptosis, thereby promoting tumor growth." (PMID 41008630, 2025). "Further investigations revealed that knockdown of the TFs candidates—DDB1, PARP1, XRCC5, RPA1, and RPA3—resulted in a significant reduction in tumor sphere formation." (PMID 40230524, 2025). "Intriguingly, in gastrointestinal cancers, MAEA overexpression paradoxically enhances chemosensitivity via promoting PARP1 ubiquitination and degradation, suggesting that MAEA’s influence on chemotherapy response is tumor type- and context-specific." (PMID 40989695, 2025).